SSTR2 (somatostatin receptor 2)
Diseases named in the same sentence as SSTR2 in open-access papers (continued):
Sharing a sentence is not in itself a finding about the gene and the disease.
brain tumors (5 papers, 2017 to 2026). "In order to augment tumor targetability, we synthesized a novel synthetic peptide against Somatostatin receptor 2 (SSTR2) which is a member of the G protein-coupled receptor (GPCR) superfamily especially overexpressed in brain tumor cells." (PMID 29029435, 2017). "Brain tumours may express high levels of SSTRs, in particular meningiomas (90% of them express SSTR2), but also astrocytomas and gliomas, making such tumours amenable to PRRT." (PMID 37345047, 2023). "Furthermore, the presence of DIM in the brain tumor region of rats treated with SSTR2 pep-DIM-NP was observed by mass spectrometry." (PMID 29029435, 2017). "PRRT has been successfully used to treat NETs due to their high expression levels of SSTR2, but PRRT may also be effective for other cancers, such as primary brain tumours, paragangliomas, or thyroid cancer." (PMID 37345047, 2023). "Computational studies suggested that out of several designed SSTR2 peptides, Ligand_15 could be used for targeted delivery of the DIM-NPs to the brain tumor region." (PMID 29029435, 2017).
glioblastoma (5 papers, 2015 to 2025). The most malignant astrocytic tumor (WHO grade IV). "Current study further questions the effectiveness of SSTR2 targeted radionuclide therapy in glioblastomas." (PMID 28467778, 2017). "In the majority of glioblastomas, the expression of SSTR2 is negative (the most commonly expressed is SSTR5)." (PMID 31432278, 2019). "We have now characterized SSTR2A expression in 101 glioblastomas and demonstrate completely negative immunostaining for SSTR2 in the majority of tumor samples." (PMID 28467778, 2017). "In contrast, another series where 50 tumor samples were assayed with a polyclonal antibody SSTR2A was reported as positive in 44% of glioblastomas, while only 10% of anaplastic and none of diffuse astrocytomas showed positive immunostaining for SSTR2." (PMID 28467778, 2017). "While autoradiographic binding studies have shown no SSTR expression in glioblastomas, immunohistochemistry (IHC) and western blot have detected increased expression of subtypes SSTR1, SSTR2, and SSTR3." (PMID 25977882, 2015). "When dichotomized, SSTR2 IHC was regarded as positive in 8 anaplastic gliomas and 1 GBMO (32%) and as negative in 6 anaplastic gliomas and 13 glioblastomas (GBMs) (68%)." (PMID 25977882, 2015).
Hyperglycemia (5 papers, 2016 to 2024). An increased concentration of glucose in the blood. "The effect of the SSTR2 antagonist ZT-01, was assessed under basal conditions of hyperglycemia (T2D animals only) and euglycemia (HFF controls only) in the absence of any manipulations to glucose levels such as those carried out for the OGTT and ITT." (PMID 38510652, 2024). "The pathophysiology underpinning PAS-induced hyperglycemia depends on its higher affinity for SSTR5 than SSTR2." (PMID 35744057, 2022). "The effect of SSTR2a on insulin secretion during hyperglycemia has been studied in SSTR2-knockout mice and in isolated cells but revealed only weak effects on insulin secretion." (PMID 33434183, 2021). "Indeed, the SSTR5:SSTR2 activation ratio has been hypothesized to be the main driver of pasireotide-induced hyperglycaemia." (PMID 26906713, 2016). "It has high affinity for SSTR-1, SSTR-2, SSTR-3 and most importantly SSTR-5 and presents hyperglycemia as a common adverse effect, but experience in malignant INSs is very limited." (PMID 34199977, 2021).
small intestinal NETs (5 papers, 2018 to 2025). "In small intestinal neuroendocrine tumors (SI-NETs), the SSTR2 gene promoter is significantly hypomethylated compared to normal tissue, accompanied by reduced levels of the repressive histone mark H3K27me3 changes that correlate with higher SSTR2 mRNA expression." (PMID 40647381, 2025). "However, one study on small intestinal NETs showed that patients with low SSTR2 expression had significantly longer survival after peptide receptor radionuclide therapy (PRRT) than patients with high SSTR2 expression." (PMID 37185426, 2023). "The expression of SSTR2, assessed by immunohistochemistry in tumor samples, was not a predictive factor for PRRT response in a study on 42 patients with small intestine NETs." (PMID 35450421, 2022).
depression (4 papers, 2020 to 2024). "Conversely, injection of SSTR2 agonist in the rodent hippocampus decreases depression-like and anxiety-like behaviors." (PMID 36161151, 2022). "SSTR2 KO mice display increased depression-like and anxiety-like behaviors together with increased cortisol levels." (PMID 36161151, 2022). "We also observed increased somatostatin receptor 2 expression in subjects with substance use disorder with alcohol in the blood at death and decreased expression in subjects with major depression." (PMID 36161151, 2022). "Some of the common down genes in maternal C57 mice and depression were for the MAP kinase pathway and some of the common down genes included: FOS, EGR1, DUSP1, BDNF, NR4A1, NR3C1, the neuropeptide somatostatin (SST), and one of the its receptors, SSTR2." (PMID 34997033, 2022).
gastric tumor (4 papers, 2018 to 2022). "We revealed that SSTR2 promoter is hypermethylated in intestinal metaplasia, dysplasia, and gastric tumors, associating with gene silencing." (PMID 36551669, 2022). "We here aimed to evaluate the extent and role of methylation at the SSTR2 promoter in inflammation and gastric tumor formation." (PMID 36551669, 2022). "Using public data, we confirmed SSTR2 promoter methylation in primary gastric tumors and intestinal metaplasia, and even aged gastric mucosae infected with Helicobacter pylori, suggesting that aberrant methylation is initiated in normal gastric mucosa." (PMID 36551669, 2022). "Among these genes, we further selected six GI hormone receptors whose expression was significantly down-regulated by 80–100% in the primary gastric tumors, including neuropeptide Y receptors (NPY1R and PPYR1), prostanoid receptors (PTGDR, PTGER2, and PTGER3), and a somatostatin receptor (SSTR2)." (PMID 30510283, 2018). "The qRT-PCR and bisulfite sequencing analyses of the six genes (NPY1R, PPYR1, PTGDR, PTGER2, PTGER3, and SSTR2) demonstrated a negative correlation between methylation and gene expression in two sets of paired gastric tumor and normal tissues." (PMID 30510283, 2018).
hepatocellular carcinoma (4 papers, 2016 to 2025). A malignant tumor that arises from hepatocytes. "This study explores the potential of SSTR2-targeted theranostics, integrating diagnostic and therapeutic strategies, for hepatocellular carcinoma (HCC)." (PMID 39857944, 2025). "The discrepancy of SSTR2 observed in Hua group between short-term and long-term treatment of Hepatocellular carcinoma using octreotide can explain the different SSTR2 expression levels in our in vivo and in vitro studies." (PMID 27825139, 2016). "This study investigates the potential utility of SSTR2-targeted theranostics in hepatocellular carcinoma (HCC)." (PMID 39857944, 2025).
lymph node metastasis (4 papers, 2021 to 2024). "In order to determine SSTR2 expression in tumors in different sites in a patient we identified 34 patients who had samples from both a primary tumor, lymph node metastasis and liver metastasis on the TMA." (PMID 33922482, 2021). "SSTR2 expression in rectal NETs was significantly correlated with favorable clinicopathologic factors, such as small size, absence of lymph node metastasis, low pT classification, low AJCC stage group, and negative chromogranin immunohistochemical expression." (PMID 38374188, 2024). "The SSTR2 expression levels did not vary significantly between primary, lymph node or liver metastases (average score primary tumor 2.18 vs. average score lymph node metastases 2.03 vs. average score liver metastases 2.24, p = 0.52)." (PMID 33922482, 2021). "Patient 8 underwent surgery and histology confirmed a SSTR2-negative lymph node metastasis of MTC." (PMID 38581480, 2024). "The stage, curability, T-factor, lymph node metastasis, tumor thrombus in the portal vein, intrahepatic metastasis, and carbohydrate antigen 19-9 (CA19-9) were found to be significant prognostic factors for overall survival, as well as the SSTR2 and Bcl2 expression pattern (p-Group H and U)." (PMID 33962620, 2021).
medulloblastoma (4 papers, 2020 to 2024). A malignant, invasive embryonal neoplasm arising from the cerebellum. "Immunohistochemical mapping of SSTR2 revealed a differential distribution pattern of SSTR2 in xenograft tumours which are confined to the cell surface in contrast to the cytoplasmic and nucleus in cultured medulloblastoma cells that possibly associated with OCT-mediated effect." (PMID 38203605, 2023). "In particular, medulloblastoma cells have a high expression of SSTR2." (PMID 34577572, 2021). "SSTR2 expression in these types of tumor opened the door to somatostatin receptor imaging in these cases, as demonstrated in a previous study by Muller and collaborators, in which the authors assessed the usefulness of SRI in pediatric patients with medulloblastoma." (PMID 34577572, 2021).
melanoma (4 papers, 2014 to 2025). A malignant, usually aggressive tumor composed of atypical, neoplastic melanocytes. "In patients with urological cancers and melanoma, SSTR2 expression by IHC has been reported as positively correlated with the response to a checkpoint blockade, suggesting SSTR2 as a potential surrogate marker to identify responders to immunotherapy." (PMID 39682120, 2024).
osteosarcoma (4 papers, 2018 to 2022). A usually aggressive malignant bone-forming mesenchymal neoplasm, predominantly affecting adolescents and young adults. "A recent study has reported potentiation of 177Lu-octreotate PRRT by PARPi in a rat pancreatic adenocarcinoma cell line that endogenously expresses SSTR2, and in the human osteosarcoma cell line U2OS that was modified to express exogenous SSTR2." (PMID 29872498, 2018). "Lastly, the untreated U2OS osteosarcoma cells, which had basal LuTate uptake that was almost 5-fold more than BON-1, exhibited a modest 1.6-fold increase in LuTate uptake after TEM treatment that was similar to that seen is high SSTR2-expressing NCI-H727 cells." (PMID 33435224, 2021).
pancreatic adenocarcinoma (4 papers, 2014 to 2023). "Previous studies have shown that SSTR2, in addition to the treatment of inflammatory diseases and arthritis, has shown some beneficial effects in acute pancreatitis, pancreatic adenocarcinomas and carcinoids." (PMID 38203605, 2023). "The radiolabelled peptides were studied in SSTR2-expressing rat pancreatic adenocarcinoma AR42J cells to investigate their internalization and specificity of the binding." (PMID 37501774, 2023). "In their animal model for pancreatic adenocarcinoma, SSTR2 overexpression led to strong up-regulation of cyclin-dependent kinase inhibitor p16, which then inhibited tumor cell cycle progression from G1 to S phase." (PMID 25010045, 2014). "In concordance with our data, human pancreatic adenocarcinomas lose SSTR2 expression." (PMID 25010045, 2014).
Anxiety (3 papers, 2020 to 2022). Intense feelings of nervousness, tension, or panic often arise in response to interpersonal stresses. "The expression of SSTR2 in the brain regions involved in anxiolytic effect in the stress model of anxiety support its role in anxiety." (PMID 32272767, 2020). "Furthermore, evidence also exists from behavioural studies showing that SSTR2 specific agonist but no other subtypes suppressed anxiety." (PMID 32272767, 2020).
atherosclerosis (3 papers, 2017 to 2025). A disease characterized by the build-up of fatty material and calcium deposition in the arterial wall resulting in partial or complete occlusion of the arterial lumen. "68Ga-DOTATATE and 64Cu-DOTATATE demonstrate high selectivity for SSTR2, favoring their use in diseases with dominant SSTR2 expression such as atherosclerosis and vasculitis." (PMID 41375754, 2025). "We confirmed that high target SSTR2 gene expression occurs exclusively among activated proinflammatory M1 macrophages in atherosclerosis and demonstrated the presence of SST2 receptors in macrophages from patients with CVD." (PMID 28385306, 2017). "In a study conducted on 42 patients with atherosclerosis, gallium‐68‐labeled DOTATATE positron emission tomography (PET) was shown to be able to bind the SSTR2 on pro‐inflammatory CD68+ macrophages." (PMID 40789673, 2025).
corticotroph adenomas (3 papers, 2013 to 2024). "While SSTR2 and SSTR4 were not detectable in corticotroph adenomas, one out of three cases showed expression of SSTR1 and one out of two for SSTR3 and SSTR5." (PMID 30627156, 2018).
liver cancer (3 papers, 2013 to 2025). An epithelial or non-epithelial malignant neoplasm that arises from the liver. "Somatostatin receptor 2 was also associated with several well-known growth-promoting proteins in liver cancer." (PMID 41002582, 2025). "Our analysis demonstrated that SSTR2 transcript levels were significantly elevated in tumor tissues compared to their normal counterparts in several malignancies, including liver cancer." (PMID 41002582, 2025). "IHC staining was performed using the anti-SSTR2 antibody HPA007264 (Sigma-Aldrich) on liver cancer tissues from 12 HCC patients." (PMID 41002582, 2025). "Our data strongly support further preclinical and clinical evaluation of SSTR2-directed PRRT in liver cancer, particularly for tumors that demonstrate high SSTR2 expression and co-expression of actionable oncogenic targets." (PMID 41002582, 2025). "Future studies should focus on validating these observations in large, independent cohorts and in vivo models, with an emphasis on preclinical investigations that evaluate SSTR2-targeted imaging and therapy in liver cancer." (PMID 41002582, 2025). "Taken together, our results suggest that somatostatin receptor 2 may contribute to liver cancer progression." (PMID 41002582, 2025). "Given the observed elevated expression of SSTR2 in liver cancer tissues compared to adjacent normal tissues, we hypothesized that SSTR2 may play a functional role in HCC tumorigenesis." (PMID 41002582, 2025). "The absence of SSTR2 and SSTR5 may explain the lack of local response to octreotide therapy in certain advanced liver cancers." (PMID 24137418, 2013).
medullary thyroid cancer (3 papers, 2019 to 2022). "As a comparison to other NET cell lines, the effect of HDAC inhibitor treatment on SSTR2 protein incidence was also determined in medullary thyroid cancer cell lines: TT and MZ." (PMID 31163616, 2019). "These include cell lines derived from pNETs (i.e. BON-1 and QGP-1), pulmonary NETs (i.e. NCI-H727), siNETs (i.e. GOT-1) and medullary thyroid cancer (i.e. TT and MZ-CRC-1), which are all characterized by their own basal SSTR2 expression levels." (PMID 33085037, 2021).
myocarditis (3 papers, 2021 to 2025). Myocarditis is a condition that is characterized by inflammation of the heart muscle (myocardium). "The biological rationale for SSTR-based imaging in myocarditis stems from the expression of somatostatin receptors, particularly SSTR2, on activated lymphocytes and macrophages—key effector cells in immune-mediated cardiac inflammation." (PMID 41375754, 2025). "In the present study, we systematically analysed the expression of SSTR2 on inflammatory cells in patients with biopsy- or explant-proven myocarditis." (PMID 39518342, 2024). "Consequently, the present study is, to the best of our knowledge, the largest available investigation concerning the expression of SSTR2 on inflammatory cells in different forms of myocarditis using histopathological techniques and Western blotting." (PMID 39518342, 2024). "Our results indicate that SSTR2 is expressed on the protein level on CD68-positive macrophages and multinucleated giant cells in different forms of myocarditis, such as LM, GCM, and CS." (PMID 39518342, 2024). "For instance, most myocarditis studies relied on MRI rather than endomyocardial biopsy, with only one biopsy-based report confirming SSTR2 expression in limited samples (<20 patients)." (PMID 41375754, 2025). "In a few of our controls, IHC staining for SSTR2 showed weak background staining without any specific link to certain cell types and/or the presence of myocardial inflammation and/or scars." (PMID 39518342, 2024).
oligodendroglioma (3 papers, 2015 to 2021). A well-differentiated (WHO grade II), diffusely infiltrating neuroglial tumor, typically located in the cerebral hemispheres. "We thus demonstrate an association between SSTR2 and oligodendroglioma component but underline that a larger study is necessary to confirm this initial finding." (PMID 25977882, 2015). "Furthermore, two anaplastic oligodendrogliomas out of the four HGGs with 1p/19q co-deletion, a biomarker strongly linked to oligodendroglial histology, also showed the most intensive SSTR2 staining." (PMID 25977882, 2015). "Previously SSTR2 expression has been connected to better prognosis in NETs, pulmonary carcinoids and oligodendrogliomas." (PMID 34307181, 2021). "Our study demonstrates for the first time that SSTR2 expression in HGGs is associated with IDH1 mutation, oligodendroglioma component, and improved PFS." (PMID 25977882, 2015). "Previous studies have not detected a clear association between SSTR2 expression and oligodendroglioma component." (PMID 25977882, 2015). "The second finding of particular interest was the positive association between SSTR2 expression and IDH1 mutation, oligodendroglioma component, and improved PFS, which indicates that SSTR2 expression may become a new biomarker in HGG useful for prognostication and therapeutic decision-making." (PMID 25977882, 2015). "By contrast, SSTR2 expression was associated with IDH1 mutation (P = 0.007), oligodendroglioma component (P = 0.010), lower grade (P = 0.005), absence of EGFR amplification (P = 0.021), and longer progression-free survival (HR 0.161, CI 0.037 to 0.704, P = 0.015)." (PMID 25977882, 2015).
pancreatic ductal adenocarcinoma (3 papers, 2024 to 2025). An infiltrating adenocarcinoma that arises from the epithelial cells of the pancreas. "In pancreatic ductal adenocarcinoma, MOR has been found to colocalize as a functional heterodimer with somatostatin receptors 2 (SSTR2), which was not specific for normal, pancreatic cells, as confirmed by the co-immunoprecipitation procedure." (PMID 39861181, 2025).
papillary thyroid carcinoma (3 papers, 2019 to 2026). "Fluorescence-activated cell sorting (FACS) of the pulmonary carcinoid cell line H727 in comparison to the papillary thyroid cancer cell line (TPC) confirmed the functional overexpression of SSTR2 expression after HDAC inhibitor treatment." (PMID 31163616, 2019).